Y_RNA (Y RNA )
Gene: Miscellaneous RNA gene on chromosome 12 (6,234,345 to 6,234,455, reverse strand). Ensembl gene ENSG00000202318.
Homologues: Orthologues: chimpanzee Y_RNA (99% identical), macaque Y_RNA (93% identical). Paralogues in human: RNY1P5 (84% identical), Y_RNA (84% identical), Y_RNA (82% identical), Y_RNA (81% identical), Y_RNA (80% identical), Y_RNA (79% identical), RNY1P1 (78% identical), RNY1P6 (78% identical), Y_RNA (78% identical), Y_RNA (77% identical), RNY1 (77% identical), Y_RNA (76% identical), and 96 more.